IL6 (interleukin 6)
Diseases named in the same sentence as IL6 in open-access papers (continued):
Sharing a sentence is not in itself a finding about the gene and the disease.
infection (continued). "In order to investigate the effect of short-term heat shock on HSP70 expression in H5N1-infected mice, we detected the expression of HSP70 as well as cytokines including IL-6, TNF-α, IFN-β, and IFN-γ with real-time PCR, western blot, and ELISA at Days 0, 1, 3, and 6 post-infection." (PMID 27379054, 2016). "In assays for a panel of cytokines, infection with rPR/8 × KYGNS did not induce overexpression of pro-inflammatory cytokines (IL-6, CCL5, and IFN-γ) on the contrary to what was observed with the two other viruses." (PMID 27846859, 2016). "Expression of several other innate immune related genes such as the β-defensin AvBD9 and chemokines RANTES and IL-8 in the lung and IL-1β and IL-6 in the spleen were not significantly altered by infection or D-CATH-2 treatment." (PMID 27229866, 2016). "In mammals, IL-6 induction through STAT3 phosphorylation downregulates FOXP3 and blocks Treg cell differentiation while maintaining the Th17 response in order to continue dealing with the infection." (PMID 27069644, 2016). "Even so, IL-6, IL-10, and IFN-β levels were all increased immediately after infection at 1 d.p.i.." (PMID 27252695, 2016). "For instance, mice lacking MyD88, the common adaptor protein for many Plasmodium-stimulated TLRs, exhibited diminished blood inflammatory cytokines (IL-6, IL-12, IFNα, IFNγ, TNF, CCL2) in several of the murine models, leading to improved resistance to these infections." (PMID 27792766, 2016). "The levels of TNF-α, IL-6 and IFN-γ tended to increase gradually as infection progressed." (PMID 27489303, 2016). "Levels of IL-1β, IL-6, CCL2, CCL3 and CCL5, which are known to play an important role during HSE, were measured in brain homogenates using magnetic bead-based immunoassays prior to (day 0) and on days 6, 8 and 10 following infection." (PMID 27930721, 2016). "Moreover, the antiviral activity can be amplified by the chemoattractant function of the chemokines which recruit leukocytes to the site of infection and activate these cells to secrete the proinflammatory cytokines (TNF-α, IL-1β and IL-6)." (PMID 27538960, 2016). "Likewise, pre-exposure to P. aeruginosa synergistically enhanced the IL-6 release following RSV infection in four out of seven donors, with a trend towards statistical significance 72 h after infection (p = 0.09)." (PMID 27259950, 2016). "For example, Beltan and the coworkers revealed a considerable induction of the synthesis of the proinflammatory cytokines IL-1, IL-6, GM-CSF, and TNFα after in vitro infection of human macrophages with only nonpathogenic mycobacteria." (PMID 27066505, 2016). "As VEGF-A and VEGFR-2 are important factors in oncogenesis, our findings suggest that ALV-J hijacks IL-6 to promote tumorigenesis, and indicate that IL-6 could potentially serve as a therapeutic target in ALV-J infections." (PMID 27852059, 2016). "To clarify the role of Dectin-2 in the host response to S. pneumoniae infection, we compared the production of proinflammatory cytokines and chemokines, such as IL-1β, TNF-α, IL-6, IFN-γ, IL-17A, and MIP-2, in BALF between WT and Dectin-2KO mice 12 h after infection." (PMID 26727976, 2016). "A lately increased cytokine IL-6, VEGF and IL-13 were at around 3 months after infection." (PMID 27830756, 2016). "However, with the exception of IL-6, serum cytokine kinetics were similar for SchuS4 and LVS infection, but of lower magnitude in comparison to lungs." (PMID 27015566, 2016). "After 60 h of infection, at the more acute phase, the bacteria had induced a substantial increase in the expression of genes for most proinflammatory cytokines, including IFN-γ, IL-1β, IL-2, IL-6, IL-8, IL-22, and TNF-α, as well as genes for IL-10 and IL-4." (PMID 27357336, 2016). "Guan and colleagues already demonstrated secretion of IL-6 und IL-8 by human periodontal ligament cells after infection with P. intermedia, but no stimulation of IL-1ß and TNF-α19." (PMID 27974831, 2016).
infection (continued). "Strikingly, five days post-infection, we found a significant defect in the percentage of TNF and IL-6 positive Ripk3-/-Casp8-/- inflammatory monocytes isolated from the mesenteric lymph nodes (mLN) of mixed BM chimeras compared with either wild-type or Ripk3-/- cells from the same animal." (PMID 27737018, 2016). "The maximum level of secretion into the supernatants was observed at 72 h after infection for both IL‐6 and IL‐8 (data not shown)." (PMID 27957326, 2016). "Through induction of IL-6 as well as chemokines such as CCL2, CXCL8, and CXCL10, Vγ9/Vδ2 T cells and MAIT cells are likely to enhance local inflammation and contribute to further recruitment of monocytes, neutrophils, and lymphocytes to the site of infection." (PMID 27527598, 2016). "Infection with both OSU and UK RVs increased the expression of IFN-β in PIE cells as well as the expression of the inflammatory cytokines and chemokines CXCL10, IL-6, IL-8 and, MCP-1." (PMID 27023883, 2016). "On the other hand, an increase in IL-6 response to S. pyogenes was observed while there was no response to BCG even after 48 h of infection." (PMID 27014727, 2016). "IL-6 and TNF-α are primary pro-inflammatory cytokines that could exhibit an acute phase response to tissue injury, infection, or inflammation." (PMID 27701469, 2016). "In addition, cytokines like IL-6, IL-1, and S100 or TNF activate MDSC at the infection site, where MDSC are noted for T-cell inhibition and defects in phagocytosis and, at least for G-MDSC, accelerated apoptosis." (PMID 27015566, 2016). "During the first 4–6 weeks after infection, the Th–1 response is stimulated by the migration of immature adult worms as characterized by increased levels of pro–inflammatory cytokines, including TNF–α, IL–1, IL–6 and IFN–γ." (PMID 27514777, 2016). "DV3P12/08 infection triggered the release of large amounts of TNF-α, IL-6, and MCP-1." (PMID 26844767, 2016). "In addition, we determined bacterial titers in homogenates of cerebellum and spleen and in blood samples from a separate set of TNFR1−/−, IL-6−/−, or TNFR1-IL-6−/− or WT mice 30 h after infection." (PMID 27057100, 2016). "The clinical evaluations and laboratory parameters (haemoglobin [Hb], white blood count [WBC], IL-6, IL-1b, TNF-alpha) did not reveal systemic signs of infection or blood loss." (PMID 27125302, 2016). "Infection with CIV alone, Sp alone or coinfection stimulated a significantly higher release of cytokines, such as interferon-gamma (IFN)-γ, interleukin 6 (IL)-6, tumor necrosis factor (TNF-α) and lymphotactin (Lptn), than was observed in the mock-infected group (PBS)." (PMID 27259293, 2016). "The serum levels of interleukin 6 (IL-6), tumor necrosis factor-α (TNF-α), and interleukin 12p70 (IL-12p70) from the three mouse groups showed a sharp peak at 8 h after infection; the peak values returned to basal levels at 12 or 16 h after infection." (PMID 27270879, 2016). "The molecules that depicted significant increases in those mAb treated-mice at 96 h after infection were CXCL1 (KC), CCL2 (MCP-1), CCL3 (MIP-1α), CCL4 (MIP-1β), CXCL2 (MIP-2), CXCL5 (LIX), IL-1α, IL-6, G-CSF, M-CSF, and TNF-α (for all, P < 0.01) and IL-1β, IL-15, IL-10, and LIF (for all, P < 0.05)." (PMID 27642235, 2016). "This indicates that PCV2 may inhibit IL-6 and TNF-α signal transduction in PBMCs in subclinical infections." (PMID 27581515, 2016). "IL-6 is also involved in the activation of the Th17 response, characterized by neutrophil recruitment and inflammation; thus, it is not entirely clear what type of immune response in C57BL/6 mice is relevant to confront infection by S. schenckii." (PMID 27051673, 2016). "Similarly, the levels of IL-6 and Mx mRNA from the rEmbp group were higher than those from the BSA control group on day 1 post-infection." (PMID 27306590, 2016).
infection (continued). "It was recently reported that IL-6Rα-deficient mice show increased resistance to P. chabaudi infection and that IL-6 trans-signaling, but not IL-6 classic signaling, contributes to a lethal outcome of infection." (PMID 26991425, 2016). "Thirty minutes post PAO1 infection, compared with negative controls, IL-6 production was significantly increased in Lyn-silenced MH-S cells, which was detected by enzyme-linked immunosorbent assay, quantitative PCR and immunoblotting, respectively." (PMID 29263906, 2016). "While the induction of these proinflammatory modulators by the two different CHIKV isolates was very similar, the expression of IL-6 and COX-2, was statistically significantly higher during infection with the more virulent isolate, T-SBY, especially late during infection (between day 4–7)." (PMID 27590311, 2016). "Reduced responses to IL-6 should serve as a negative feedback mechanism for preventing deleterious effects of excessive hormone signaling during infections." (PMID 27484112, 2016). "Our data showed that IL-6 was highly produced by BCG infection at MOI 1 while no expression was observed with infection at MOI 0.1." (PMID 27833923, 2016). "In this study, we found that the infection of influenza A virus subtype A/Quali/Hong Kong/G1/97 (H9N2) on HPMECs induced excessive production of various pro-inflammatory cytokines and chemokines, including IP-10, RANTES and IL-6 in a time-related manner." (PMID 26732368, 2016). "By qRT-PCR, we found that there were no obvious up-regulations in the expressions of IL-1β and IL-6 during the early phase infection of CK/SD/w3 and CK/SD/w4." (PMID 27446066, 2016). "This indicates an unspecific reaction to bacterial infection, suggesting that IL6 expression was in response to infection, but not in an OP-specific manner, which affects all compartments of the lung." (PMID 27282780, 2016). "The observation of an increase in only one (IL-6) of the 13 cytokines investigated is not surprising in the context of our infection model." (PMID 25965781, 2015). "Th2 cytokines such as IL-5 and IL-10 were found to be increased during the early stages of infection (days 3–4 pi), while Th1 cytokines such as IL-6, IFNγ, and IL-18 did not increase until later in disease (days 6–9 pi)." (PMID 26512687, 2015). "Astrocytes support neuronal function by secretingneuropoietic factors such as IL-6.However, no significant production of IL-6 between wild-type andCCR5−/− primary astrocytes was seen upon infection withN." (PMID 25558986, 2015). "Furthermore, as compared with JEV-WT infection, even with serum-containing medium, JEV-NS5-M19A infection triggered significantly lower levels of IL-6 and TNF-α while producing slightly less viral RNA." (PMID 25816318, 2015). "The amount of IL-6 produced by DV2-infected TLR6-/- murine peritoneal macrophages was higher than that of the mock-infected, suggesting that the stimulation by DV NS1 protein only contributed partially to the amount of IL-6 detected in the DV2 infection." (PMID 26226614, 2015). "The induction of the chemokine genes IP-10 (CXCL10) and I-Tac (CXCL11) and of the proinflammatory cytokine gene IL-6 was observed in a genome wide mRNA microarray analysis at 48 h post HAdV-B14p1 infection, but not in HAdV-C5 infected control cultures." (PMID 26168049, 2015). "Moreover, cytokine levels, including interleukin (IL)-1β and IL-6, were reduced in the supernatants following RV14 infection." (PMID 26462747, 2015). "The elevated levels of IFNγ, IL6 and IL12 on d7 of infection were mirrored histologically by the presence of haemozoin-containing phagocytes, several immunoblasts (blast T cells) in the peri-arteriolar lymphatic sheath area and B-cell activation (centroblasts) in germinal centres." (PMID 25890318, 2015).
infection (continued). "Real-time quantitative polymerase chain reaction showed that the expression of TLR3, TLR7, RIG-I, MDA5, IL-1β, IL-2, IL-6, IL-8, IFN-alpha, IFN-beta, IFN-gamma in the lungs was significantly greater than in the respective thymus genes during the early post infection stage." (PMID 26635752, 2015). "Infection with R. massiliae did not induce increased secretion of IL-8 and IL-6 at 48 HPI compared to uninfected controls." (PMID 26394396, 2015). "The serum concentration of IFNγ, TNFα, IL-10 and IL-6 only started to increase substantially on day 6 post-infection, and no apparent difference was observed in the serum levels of IL-1β." (PMID 25768944, 2015). "While MHV68 latency did not rescue the induction of Tnf or Il6 transcripts in HOIL-1 KO mice following infection with Listeria, Il12b transcript levels were increased approximately twofold, and were comparable to levels in control mice." (PMID 25599590, 2015). "Secretion of IL-10 and TNF-α induced by AO3 and AR39 infection was also the same (data not shown), while IL-6 secretion was higher for AR39 but only for one MOI and only at 35 °C." (PMID 26494400, 2015). "This scenario may occur during an infection resulting in a sustained production of TGF-β and IL-6, thereby increasing Th17 cells." (PMID 25601923, 2015). "A cut-off value of IL-6 of 297 pg/mL presented sensitiveness of 62%, positive predictive value (PPV) of 50% and negative predictive value (NPV) of 70% (p = 0.016) for the identification of infection in neutropenic patients." (PMID 26543528, 2015). "Patients with infection showed higher serum IL-6 than those without complication after surgical injury." (PMID 26502877, 2015). "In contrast to D39, D39Δcps did not induce TNF-α and IL-6, and triggered low levels of KC in the lung 6 hours after intranasal infection." (PMID 25700108, 2015). "Expression of Il-6 mRNA was modestly up-regulated in LCMV-WE infected mice; still it was statistically different (p<0.05) at early time point in comparison with LCMV-ARM infection." (PMID 25822203, 2015). "Therefore, qRT-PCR analysis of IFNβ, OAS1, MxA, TNFα, IL-6 and viral RNA (vRNA) expression was performed in the context of WNVNY99 and WNVNSW2011 infections." (PMID 25884341, 2015). "Moreover, significant elevation of IL-6 and INF-gamma levels and a tendency to higher levels of TNF-alpha in serum was observed after infection with the S. aureus wild-type strains at the end of the experiment." (PMID 25644616, 2015). "γδ T cells can secrete IL-17 during infection, which is independent of IL-6, an essential cytokine for driving the development of Th17 cells." (PMID 26071315, 2015). "At 30 h post infection, IL-10 and KC levels were lower in C/EBPδ−/− brain homogenates, whereas brain IL-6, TNF-α, IL-1β, and MIP-2 levels were not significantly different between the two genotypes." (PMID 25958220, 2015). "In patients without infection LBP versus IL-6 at 3 d (P = 0.003) and IL-6 versus CRP at 3 d (P = 0.003) were significantly correlated." (PMID 25613713, 2015). "We previously reported that IL-6 was induced via TLR2-dependent pathways in C. muridarum-infected OE cells, and our findings suggest a more critical role for NF-κB in the Chlamydia-induced synthesis of IL-6 throughout the course of infection." (PMID 25798928, 2015). "Indeed, as compared with CP-deficient mice, the wild type mice produced significantly higher levels of proinflammatory cytokines: IL-1β, IL-6, and MIP-2 at 2 h, and all 6 cytokines at 12 h post infection." (PMID 26147796, 2015). "On the other hand, in HEK293 cells, IL-6 was upregulated at comparable levels both in mRNA transcripts and concentrations in infections with miRT-H1N1, scbl-H1N1, or wt H1N1, indicating that proinflammatory cytokine IL-6 was induced distinctly with the mutant virus only in HBE cells." (PMID 25788763, 2015). "MCP-1, IL-6 and MIP-2 levels were measured in BAL fluid at day 9 post-infection across the 24h day." (PMID 25923474, 2015).
infection (continued). "While TRAF-6 expression was not altered at this time point of infection, the level of mRNAs corresponding to IL-6 and IFN-β were significantly upregulated in DENV-2 infected A549 cell cultures." (PMID 25962098, 2015). "In both knockout strains, IL-6 was detected in the plasma at day 6 of infection at levels not significantly different from those of infected WT C57BL/6 controls." (PMID 25763578, 2015). "Specifically, cytokines and chemokines including IL-6, IL-8, TNF-α, as well as CCL-5, MIP-3α, and IP-10 were significantly induced, providing an immunopathological basis for liver pathology, deteriorated by infection-induced apoptosis." (PMID 26134299, 2015). "When the median serum concentrations of the cytokines were compared between the two control groups, a significant statistical difference was found only for IL-6 and IL-8, which were higher in the group of patients with non-IE infections." (PMID 26225421, 2015). "The signature also performed better than a wide range of host-proteins with an established role in the immune response to infection, including bacterial-related (e.g. TREM, IL-6 and IL-8), virus-related (e.g. IFN-γ and IL-2), and inflammation-related (e.g. IL-1a and TNF-α) proteins (P<10–8)." (PMID 25785720, 2015). "H1N1pdm09 infection alone did not induce release of IL-1β or IL-6 PBMCs from either pregnant or non-pregnant women when compared to media." (PMID 25831059, 2015). "The expression of Sbi significantly contributed to IL-6 production and modulated CXCL-1 expression as well as neutrophil recruitment to the site of infection, thus demonstrating for the first time its relevance as a pro-inflammatory staphylococcal antigen in an in vivo model." (PMID 26126119, 2015). "Studies on the role of the IL6 −174 G>C SNP in RSV-infected macrophages showed GC heterozygotes and CC homozygotes as high IL6 production genotypes, correlated with the infection, while among RSV-infected patients, the CC genotype at the analyzed SNP was associated with low IL6 levels." (PMID 26385345, 2015). "Although the mechanisms by which IL-6 contributes to antibacterial activity are still not clear, the role of IL-6 against infection is commonly acknowledged." (PMID 26223356, 2015). "The concentrations of all cytokines and chemokines in the spleen 20 hours after infection (IL-6, IL-10, CXCL1, and CXCL2) were not different among all three groups studied." (PMID 25563481, 2015). "Besides TNF-α, the induction of other cytokines including IL-6 and IL-1β was also observed in both Huh7 cells and PHH at 2 hours post-infection." (PMID 26023919, 2015). "A careful dissection of the transcription profile by day 1 pi in tissues from E75CV1-infected pigs, allowed the confirmation of the significant up-regulation of CD163, IL-1β, IFN-γ, IL-5, IL-6, IL-10, IL-12p40, TNF-α and TGF-βR1 and the down-regulation of DEFB2, immediately after E75CV1 infection." (PMID 26589145, 2015). "Similarly, in SUDV infection, the pro-inflammatory cytokines IL-1α, IL-6, MCP-1, M-CSF, MIP-1α, and IL-8 are increased in fatal infection, as is nitric oxide." (PMID 26426036, 2015). "Furthermore, the expression of IL-6 and IFN-beta in the lungs and thymuses following infection with SS-10 was greater than that with NH-10 at 24 and 48 hpi." (PMID 26635752, 2015). "Using cells only treated with IL-33 or cells only infected with HTNV as controls, the mRNA expression of IL-1β, IL-6, IL-8, CCL2, CCL20, CXCL1, CXCL2, and CX3CL1 was significantly induced in HUVECs prior to infection with HTNV (MOI = 1) for 48 h and then exposed to IL-33 (20 ng/ml) for 6 h." (PMID 25658420, 2015). "Proinflammatory cytokine IL-6 has been reported to be dominant in H1N1pdm infected patients or HBE cells and may be involved in viral pathogenesis in infection." (PMID 25788763, 2015).